CCDC126 (coiled-coil domain containing 126)
Synonyms: FLJ23031
Tractability: Antibody: UniProt places it where antibodies can reach, with high confidence; UniProt predicts a signal peptide or a membrane-spanning region; its Gene Ontology location is reachable by antibodies, with medium confidence. PROTAC: ubiquitination databases record sites on it.
Gene: Protein-coding gene on chromosome 7 (23,597,377 to 23,644,712, forward strand). Ensembl gene ENSG00000169193.
Subcellular location: Secreted
Subcellular location (Human Protein Atlas): Golgi apparatus; Predicted to be secreted
Gene Ontology:
Cellular component: membrane; extracellular region
Genetic constraint (gnomAD): Loss-of-function variants: 4 observed, 10.43 expected, observed/expected ratio (o/e) 0.38, 90% interval 0.19 to 0.88. The upper end of that interval is the gene's LOEUF score, 0.88, which puts it in group 3 of 6, group 1 being the genes least tolerant of losing a copy. Missense variants: 142 observed, 160.83 expected, observed/expected ratio (o/e) 0.88, 90% interval 0.77 to 1.01. Synonymous variants: 58 observed, 63.2 expected, observed/expected ratio (o/e) 0.92, 90% interval 0.74 to 1.14.
Homologues: Orthologues: chimpanzee CCDC126 (99% identical), macaque CCDC126 (99% identical), dog CCDC126 (96% identical), pig CCDC126 (96% identical), guinea pig CCDC126 (95% identical), rabbit CCDC126 (94% identical), mouse Ccdc126 (89% identical), rat Ccdc126 (89% identical), tropical clawed frog ccdc126 (75% identical), zebrafish ccdc126 (53% identical), Caenorhabditis elegans gly-2 (19% identical). Paralogues in human: MGAT5 (28% identical), MGAT5B (26% identical).
Diseases named in the same sentence as CCDC126 in open-access papers:
CCDC126 is named in the same sentence as 2 diseases in open-access papers, as found by Europe PMC text mining. Sharing a sentence is not in itself a finding about the gene and the disease. The quoted sentences say what the papers report.
retinal disease (2 papers, 2010 to 2011). "Furthermore, we identified three human retinal disease loci mapped in close proximity to certain down-regulated genes in the Otx2 CKO retina including Ccdc126, Tnfsf13 and Pitpnm1, suggesting that these genes are possibly responsible for these diseases." (PMID 21602925, 2011).
dominant cystoid macular dystrophy (1 paper, 2011). "Human CCDC126 is located on 7p15.3 where dominant cystoid macular dystrophy has been mapped." (PMID 21602925, 2011).